CXCL1 (C-X-C motif chemokine ligand 1)
Diseases named in the same sentence as CXCL1 in open-access papers (continued):
Sharing a sentence is not in itself a finding about the gene and the disease.
infection (continued). "Among these genes, several encode chemokines (IL8, CXCL1, CXCL10, CXCL11, CXCL9, PF4, PPBP), a family of small proteins that play important roles in the immune system through leukocyte recruitment, cell communication and cell activation during infection." (PMID 26791855, 2016). "However, IL-36R deficient mice infected with M. bovis BCG showed similar survival and control of the infection as compared to wild-type mice, although their lung pathology and CXCL1 response were transiently different." (PMID 25950182, 2015). "The expression of Sbi significantly contributed to IL-6 production and modulated CXCL-1 expression as well as neutrophil recruitment to the site of infection, thus demonstrating for the first time its relevance as a pro-inflammatory staphylococcal antigen in an in vivo model." (PMID 26126119, 2015). "To test this hypothesis, we compared the levels of CXCL1 in kidneys homogenates of C5aR1−/− and C5aR2−/− mice with that of wild type mice at 12 h of infection." (PMID 26512700, 2015). "Our findings suggest that defects in CFTR may increase susceptibility of mice to lung infections with the highly mucoid serotype 3 Sp despite similar lung histopathology and levels of TNF- α and CXCL1/KC produced early in infection." (PMID 26469863, 2015). "CXCL1 specifically targets neutrophils through the receptor CXCR2 promoting chemotaxis and activation of neutrophils but despite the initial significant increase of CXCL1 expression in Fas- and FasL-deficient mice at 3rd day of ECTV infection, later during infection we observed an opposite effect." (PMID 25873756, 2015). "The mortality defect observed in MyD88(−/−) mice can be significantly ameliorated by administration of a single dose of recombinant CXCL1 at the onset of infection, consistent with the notion that MyD88-coupled signals act to orchestrate neutrophil recruitment." (PMID 25621893, 2015). "The increase in susceptibility of the myeloid deficient HIF1α mice to A. fumigatus was in part due to decreased early production of the chemokine CXCL1 (KC) and increased neutrophil apoptosis at the site of infection, resulting in decreased neutrophil numbers in the lung." (PMID 25255025, 2014). "Importantly, vNA-Δ infection only induced low level of type I interferons and chemokines CXCL1/KC and CCL2/MCP-1 in epithelial cells, leading to a reduced influx of leukocytes and pulmonary injury." (PMID 24927156, 2014). "Furthermore, by 48 hrs of infection the increase in CXCL1 levels in Lum−/− infected corneas was much lower than Lum+/−." (PMID 23358433, 2013). "However, 24 and 48 hrs after infection Cxcl1 transcript levels were significantly higher in the knockout infected corneas - a trend that was just the opposite of final chemokine levels measured by ELISA." (PMID 23358433, 2013). "Six hrs after infection Cxcl1 expression was higher in the Lum+/− compared to Lum−/− corneas." (PMID 23358433, 2013). "The levels of CXCL1, CXCL10, CCL1, CCL3, IFN-γ, TNF-α and IL-6 were significantly increased in the lungs of RSV-infected IL-10-deficient mice compared to control mice on day 8 post infection." (PMID 22393401, 2012). "IL-6, G-CSF, and CXCL1 were significantly increased in the lung homogenates of neutrophil depleted mice compared to lung homogenates of isotype control antibody treated mice, suggesting an attempt by the host to recruit neutrophils to the site of infection." (PMID 23216912, 2012). "Therefore, MyD88-dependent signal(s) appear responsible, in part, for IFN-γ, IL-6, and CXCL1 expression during late infection, although the mechanism(s) involved for targeting these factors remain to be identified." (PMID 22879997, 2012). "Therefore, we determined the expression of cytokines involved in neutrophil recruitment, including IL-6, G-CSF, and CXCL1, within the lungs of neutrophil depleted and isotype control antibody treated mice on day 7 post-infection with C. neoformans strain H99γ." (PMID 23216912, 2012).
infection (continued). "Similarly, the chemokines RANTES (CCL5) and KC (CXCL1) were increased with infection to a similar degree in wild type and CAT2−/− mice." (PMID 22194986, 2011). "This conclusion is supported, at least in part, by the results of Sukumaran and colleagues, who reported the upregulated expression of chemokine genes encoding CXCL1, CXCL2, CXCL3, CXCL8, CCL3, CCL4 and CCL20 after infection of PMN with Anaplasma phagocytophilum." (PMID 17875202, 2007). "Macrophages migrate to the infection site via chemotaxis, where they recognize and phagocytize fungal pathogens while producing various pro-inflammatory cytokines and chemokines, including TNFα, CXCL1, CXCL2, CCL2, and IL-1β, thereby promoting inflammation and immune defense." (PMID 41190069, 2025). "However, infection reduced the expression of several chemokines upregulated by 4T1, including monocyte recruitment factors Csf1, Ccl3, Ccl6, Ccl9, Ccl24 and EMT-associated Cxcl1." (PMID 40547518, 2025). "Indeed, in vivo, a complex network of soluble (e.g., chemokine gradients) and solid (e.g., ECM proteins, epithelial cells) cues guides maturation and migration of neutrophils from the BM to sites of infection, with the chemokines CXCL1 and CXCL2 being the most potent neutrophil attractants in vivo." (PMID 40467528, 2025). "Interestingly, lactoferrin and CXCL1 were significantly higher than healthy controls two weeks prior to detectable infection (p = 0.045 and 0.021), suggesting an immune response is triggered well before C. trachomatis reaches a high enough bacterial load to be detected by 16s rRNA PCR." (PMID 37862368, 2023). "This altered response was associated with increased gene expression of neutrophil chemokines Cxcl1 and Cxcl2 in whole lung homogenates, elevated concentrations of circulating granulocyte-colony stimulating factor (G-CSF), and higher neutrophil numbers in the lung 24 hours after infection." (PMID 35603143, 2022). "Flow cytometric analysis of infected lung tissue showed a nearly complete absence of neutrophil influx during the early infection phase (10 dpi) which can be linked to the downregulation of Cxcl5 and lack of Cxcl1 and Cxcl2 upregulation responsible for neutrophil chemotaxis during inflammation." (PMID 36400767, 2022). "Our results show that ethanol-exposed mice had a higher pulmonary bacterial burden at 24 hours after infection despite increased numbers of pulmonary neutrophils and correspondingly higher expression of chemokines involved in neutrophil recruitment, such as Cxcl1 and Cxcl2." (PMID 35603143, 2022). "Because of the well-established role of neutrophils in the clearance of staphylococcal lung infections, we hypothesized that increasing neutrophil recruitment to the lungs of fibrotic mice by treating with recombinant CXCL1 (rCXCL1) during infection would rescue bacterial clearance." (PMID 34990413, 2022). "Genes encoding CXCL1 (GRO1) and CXCL8 (IL-8) showed the highest changes in expression in cells infected with the NADL (cp) strain, which in the case of CXCL8 was confirmed by RT-qPCR, while the chemokine signaling pathway was enriched by genes with increased expression 72 h after infection." (PMID 35746747, 2022). "Thus, it is logical to speculate that in the absence of GSDMD, either a decrease in IL-1β mediated weak protection or an increase in Cxcl1 exacerbated infection." (PMID 34011393, 2021). "Thus, mouse strain, L. major strain, route of infection and timing of CXCL1 release may all contribute to the fate of the infection and overall pathology." (PMID 31260451, 2019). "Indeed, infection with E. coli 127 caused a dramatic increase in the levels of G-CSF and CXCL1 in plasma, whereas none of the other bacterial strains tested caused significant upregulation of these compounds." (PMID 27713743, 2016).
infection (continued). "CXCL1 rapidly increased 45-fold 3 h post-infection and then decreased throughout the remainder of the time course, which was in accordance with the development of pleuropneumonia; therefore, CXCL1 might be used as a novel biomarker to test the course of the disease in mice." (PMID 27046446, 2016). "The chemokine MCP-1 (CCL2), which contributes to monocyte recruitment to sites of infection, was significantly higher at all time points in the propofol-treated groups, as were the eosinophil chemoattractant eotaxin and the neutrophil chemoattractant KC (CXCL1)." (PMID 26381144, 2015). "However, later during the infection CXCL1 levels were significantly higher in wt mice." (PMID 24648449, 2014). "Owing to their strategic location in close proximity to the site of infection, tissue-resident macrophages are upon the primary inducers of an inflammatory reaction and as such promote the egress of neutrophils from the circulation by secreting chemokines including CXCL1 and CXCL2." (PMID 24755316, 2014). "However, Cxcl1 expression was higher in the Lum−/− corneas at the later stages of infection, suggesting that reduced CXCL1 levels in the Lum−/− infected corneas may contribute to a feedback up regulation of gene expression." (PMID 23358433, 2013). "MRNA levels of genes encoding for chemokines (CXCL1 and CXCL5), cytokines (IL-10, IL-15 and IL-32), pattern recognition receptors (TLR1) and innate signaling molecules like IRAK3 and TRAF6, were all increased after MVA-C infection in comparison with MVA-WT-infected cells." (PMID 22536391, 2012). "Furthermore, cytokine analysis showed that the IFN-γR−/− mice had significantly reduced levels of pro-inflammatory (IL-1α, IL-1β, and IL-6), IL-12p40, IL-17, and chemokine (G-CSF and CXCL1) production compared to WT mice during infection with C. neoformans strain H99γ." (PMID 21359196, 2011). "As demonstrated here, the expression of IL-8/CXCL8, Gro-α/CXCL1, MCP-2/CCL8 and MIP-3α/CCL20 was compromised in LPS-stimulated IRAK4-deficient monocytes, suggesting a diminished recruitment of neutrophils, monocytes, lymphocytes, basophils and eosinophils to sites of infection." (PMID 20105294, 2010). "Additionally, we show that infected Dectin-1−/− corneas have impaired IL-1β and CXCL1/KC production, resulting in diminished cellular infiltration and fungal clearance compared with control mice, especially during infection with clinical isolates expressing high β-glucan." (PMID 20617171, 2010). "Transcriptomic analysis results showed that NC infection activated the interleukin (IL)-17 and tumor necrosis factor (TNF) signaling pathways, increasing the expression of chemokines (CXCL1/2/3) and inflammatory genes (FOSB)." (PMID 41669237, 2026). "Of these, CCL20, CXCL10, CXCL1, CXCL8, and IL-18 showed higher levels compared to uninfected epithelium 24 h after infection." (PMID 40586572, 2025). "Quantitative PCR analysis revealed increased mRNA levels of proinflammatory cytokines and chemokines (Tnf, Il6, Il1b, Ccl2, Cxcl1, and Cccl2) in SARS-CoV-2-infected lungs compared with those in naïve lungs on days 2 and 5 post-infection." (PMID 40162785, 2025). "On day 3 post-infection, cytokine profiling revealed significantly higher levels of IFN-α, IFN-β, TNF-α, CXCL-1, and IL-6 in the lungs of mice infected with the G-extended virus compared to the Δ7AA virus." (PMID 40076707, 2025). "Taken together, our findings indicate that the activation of the C5a–C5aR1 axis in astrocytes facilitates the neuropathological changes resulting from EV-A71 infection, emphasizing the potential role of p38 MAPK-mediated CXCL1 production in these alterations." (PMID 39679722, 2025). "Macrophages express CXCR-2, which facilitates the release of chemokines such as CXCL-1 and CXCL-2 to recruit T cells to sites of inflammation or infection." (PMID 40585992, 2025).
infection (continued). "In order to investigate the impact of HP on the expression of METTL3 and CXCL1, we co-cultured HP with human gastric epithelial cells (GES-1) at varying multiplicities of infection (MOI) for 24 h." (PMID 40825934, 2025). "Only six mediators, ADA, CXCL1, CCL20, MCP-3, PD-L2, and TNFSF14, differed between the “infection-free” and actively infected groups." (PMID 41387890, 2025). "Our results showed that alveolar concentrations of CXCL1 and CXCL2 were indeed reduced in animals treated with SRT1720, as early as 24 h post-infection." (PMID 41096578, 2025). "In the case of MHV-JHM infection, changes in expression (from 0% to 100%) were visible in IL-6, IL-18, IL-33, ENA-78 (CXCL5), GRO alpha (CXCL1), IP-10 (CXCL10), MCP-1 (CCL2), MIP-1 beta (CCL4), MIP-2 alpha (CXCL2), RANTES (CCL5), and TNF alpha." (PMID 40358160, 2025). "In this USUV infection model, cytokines CXCL10, CCL11, CXCL1, and G-CSF peaked in the brain at later time points." (PMID 41472308, 2025). "Western blot and RT-qPCR analysis revealed that following HP treatment, the expression of CXCL1 in GES-1 cells progressively increased, showing a correlation with both the multiplicity of infection (MOI) and exposure duration." (PMID 40825934, 2025). "Its downstream effects include upregulation of chemokines such as CXCL1 and CXCL8, which recruit neutrophils to sites of infection, and stimulation of epithelial cells to produce antimicrobial peptides." (PMID 40917923, 2025). "The heightened infection risk in GD may be attributable to dysfunction of immune cells, including monocytes, macrophages, dendritic cells, T cells, and B cells, as well involvement of cytokines, such as MCP1/CCL2, CXCL8/IL8, CXCL1, IL-1β, IFNγ, and TNFα, are implicated in GD progression." (PMID 40980139, 2025). "Our results indicated that infection induced the expression of proinflammatory mediators IFN-γ, CCL5, CXCL1, and IL-6 only in the brain." (PMID 39907280, 2025). "The chemokines (CCL2, CXCL1, CXCL8, and CCL20) facilitate the recruitment of monocytes and neutrophils to the site of infection." (PMID 40570043, 2025). "Expression of IL-6, IL-8 (CXCL8), CXCL1, CXCL2, and CCL-20, which are known to be expressed in the respiratory epithelium upon infection, was assessed." (PMID 38756230, 2024). "The expression levels of CXCL1, CCL17, and CCL20 were significantly upregulated 21 days after infection with the cdh1Δ mutant strain, indicating a pronounced activation of lung tissue recruitment of neutrophils and enhanced Th2 and Th17 immune responses." (PMID 39728387, 2024). "In uninfected animals, Pam3CSK4 induced Cxcl1 approximately 10-fold, similar to the 1 PFU infection and reflecting our RNAseq results." (PMID 38935789, 2024). "Our results show that CC chemokine receptors and their ligands, which are necessary for neutrophil mobilization and recruitment to the lungs during infection, are down regulated in human CHIP carriers (e.g., CXCL1, CXCL5) and mice (e.g., CCR2, lung CCL2)." (PMID 38573824, 2024). "By 16 hours after infection, chemokine expression was increased in both WT CHIKV–infected WT and MARCO–/– mice in comparison with mock-infected mice; however, Ccl2, Cxcl1, and Cxcl9 expression remained significantly higher in the dLN of WT mice." (PMID 38194268, 2024). "Next, we evaluated G-CSF, CXCL1 and CXCL2 in circulation, as these are key cytokines regulating the mobilization of neutrophils out of the BM in response to injury or infection." (PMID 39509414, 2024). "At 96 h, all drug-treated mice displayed significant decreases (p < 0.01) in the inflammatory markers CXCL1 and TNF-α compared to the positive infection controls, and this was dose-dependent." (PMID 39759447, 2024). "In contrast, higher levels of pro-inflammatory factors like IL-6, GM-CSF and CXCL1 were observed in BALF along with lower amounts of IFNγ and IFNγ-producing T-cells one day post-infection." (PMID 39472590, 2024).
infection (continued). "Analysis of cytokines indicated a global PCLS age-effect and PAO1 infection-effect for CXCL1, IL-6, and IL-1β, while for TNF-α only a global infection-effect was observed." (PMID 38178102, 2024). "Numerous proinflammatory cytokines exhibited decreased expression in Omicron-infected BSs compared to those infected with the WT virus, including IL6, CXCL1, CXCL2, and IL1B, which play a crucial role in attracting immune cells to infection sites." (PMID 38741604, 2024). "Potential mechanisms underlying the anti-tumorigenic effects of CAPE involve the reduction in inflammation induced by ETBF infection and the inhibition of the BFT-mediated CXCL1/NF-κB pathway in colonic epithelial cells." (PMID 39330861, 2024). "We selected five cytokines, including CXCL-1, CXCL-2, IL-6, IL-8, and CCL-20, and determined their expression levels 24 h after infection using qPCR." (PMID 38756230, 2024). "IL-8 and CCL3 were produced at significantly increased levels compared to mock infection, with trends for IL-6, CXCL1, and CXCL10, at 12 h post-infection." (PMID 39599904, 2024). "We found that the transcription levels of CXCL1 and CXCL2 were strongly increased in Trim26–/–mice at 1–5 days post-infection." (PMID 38166150, 2024). "Following initiation of UTI, there were no increases in these cytokines, or in IL-17 or KC (CXCL1), measured in the kidneys of vehicle-treated mice, likely reflecting that whole-kidney cytokine analysis is insensitive to changes associated with modest and localized infection." (PMID 38206009, 2024). "We found that TMAO aggravated the release of several key cytokines (IL-1β and IL-6) and chemokines (IL-8, CXCL1 and CXCL6) from bladder epithelial cells during a CFT073 infection." (PMID 37111409, 2023). "Histopathology and inflammatory genes (Nos2, Il-1β, Tnf-α, and Cxcl1) were elevated and persisted in the large intestine of muMT mice compared with WT mice during chronic ETBF infection." (PMID 38203534, 2023). "The combination treatment with both TMAO and CFT073 had significant additive effects on the release of CXCL11 and CCL20 and synergistic effects on the release of IL-8, CXCL1, and CXCL6 compared to CFT073 infection alone." (PMID 37111409, 2023). "Infection with this bacterium was shown to increase the production of IFN-γ, TNF-α, and chemokines such as CCL3, CCL4, CCL5, CCL11, and CXCL1." (PMID 38139161, 2023). "However, B6.Nlrc4–/– mice challenged with ΔospC3 S. flexneri were less susceptible to infection, exhibiting significantly less weight loss, a >10-fold decrease in IEC colonization, reduced cecum shrinkage, and a decrease in CXCL1 relative to WT-infected B6.Nlrc4–/– mice." (PMID 36645406, 2023). "The results demonstrated that untreated A549 cells infected with B. pseudomallei expressed significantly higher amounts of MIF, PAI-1, IL-18, CXCL1, CXCL12 and IL-8 when compared with uninfected cells at 12 h post-infection." (PMID 36758060, 2023). "By day 2 after infection, significant elevations in the levels of interleukin-1β (IL-1β), TNF-α, IL-6, IFN-γ, IFNα, IFNβ, CXCL1, CCL2, and CCL5 were detected in the airways of influenza virus–infected mice." (PMID 37683004, 2023). "Neutrophils were found to follow a CXCL1 and/or CXCL2 gradient to sites of infection and stimulation further results in the release of proteases and ROS." (PMID 35529856, 2022). "In both iBEC-LMC and iBEC monocultures, CXCL8, CXCL1, CXCL2, and CCL20 were upregulated during the time course of infection, with higher upregulation of CXCL8 and CXCL1 in the monoculture model at 24 h p.i.." (PMID 36289516, 2022). "We found the levels of CXCL1, IL-6, IL-1β, CCL3 and CCL4 were higher in the kidney homogenates of female mice infected with the eng1 strain at days 1 and 4 post-infection in comparison to that infected with the ENG1 strain." (PMID 34995333, 2022).